TGFB1 (transforming growth factor beta 1)
Diseases named in the same sentence as TGFB1 in open-access papers (continued):
Sharing a sentence is not in itself a finding about the gene and the disease.
autoimmune disease (244 papers, 2006 to 2025). A disorder resulting from loss of function or tissue destruction of an organ or multiple organs, arising from humoral or cellular immune responses of the individual to their own tissue constituents. "TGFβ1 is a pivotal protein in the pathogenesis of a number of autoimmune disorders and its dysregulation is also increasingly implicated in the risk of developing RA." (PMID 29340042, 2017). "Phenotypic assessment of the regulatory populations in autoimmune diseases led to the description of various subtypes with IL10- or TGFβ1-dependent suppressive mechanisms." (PMID 36973425, 2023). "Bregs suppress a variety of immune pathologies including autoimmune diseases through the production of interleukin (IL)-10, IL-35, and transforming growth factor beta 1 (TGFβ1)." (PMID 32213346, 2020). "In the context of autoimmune disease, IL-6 in combination with TGFβ1 promotes the differentiation of Th17 cells." (PMID 32934336, 2020). "In a different approach, parasitic worms were found to secrete a TGFβ1-mimicing protein that amplified Tregs in vivo, raising the possibility that this can be developed as a biologic medication for autoimmune diseases and transplantation." (PMID 29963051, 2018). "TGFβ1 is immunosuppressive and can be protective in various pathologies including autoimmune diseases." (PMID 24626736, 2014). "The restriction of gene inactivation to fibroblasts and related collagen‐producing mesenchymal cells, as well as the temporal control achieved through tamoxifen induction, avoided the generalised autoimmune disease described previously for mice with a complete Tgfb1 gene ablation." (PMID 40652530, 2025). "Regardless, methods including TGFβ1 stimulation show promise as a potential treatment avenue for both T1DM and several other autoimmune diseases." (PMID 29963051, 2018). "Pro-inflammatory cytokines, such as TNF or IL12A, the T-cell activation molecule CD28, the regulatory molecules IL10, TGFB1 or the adhesion molecules ITGA4 and ITGB1 have all been evaluated previously as therapeutic targets for autoimmune diseases, including MS." (PMID 18030350, 2007). "Thus, mice lacking TGFβ1 or mice with T cell-specific deletion/inhibition of TGFBR2 or combined SMAD2/3-deficiency develop an early onset, multifocal and fatal autoimmune disease." (PMID 36829573, 2023). "Correlations between T1DM and other autoimmune diseases has been weak, but there is genetic evidence that genes of the immunoregulatory pathways, such as Foxp3, IL-2 and its receptors, CD28, and TGFβ1 and its receptors may play critical roles in the onset of T1DM." (PMID 29963051, 2018).
osteosarcoma (224 papers, 2000 to 2026). A usually aggressive malignant bone-forming mesenchymal neoplasm, predominantly affecting adolescents and young adults. "Interestingly, osteosarcoma tumors tend to express higher amounts of TGFβ1 and TGFβ3, which have been associated with disease progression." (PMID 33809018, 2021). "In a previous study, we demonstrated that osteosarcoma cell-derived EVs can induce lung fibroblast reprogramming in vitro and direct fibroblast activation and differentiation towards a myofibroblast/cancer-associated fibroblast phenotype through EV-associated TGFβ1 and SMAD2 pathway activation." (PMID 33233625, 2020). "Meanwhile, osteosarcoma-derived EVs enriched in TGFβ1 activated lung myofibroblast/CAFs as demonstrated by increased α-SMA expression and FN production." (PMID 37350937, 2023). "Through experiments in vitro and vivo, we found that miR-744-5p was remarkably downregulated in osteosarcoma, and it suppressed the proliferation, migration, and invasion of osteosarcoma cells by negatively regulating the TGFB1 and p38 MAPK signaling pathways." (PMID 35593122, 2022). "In conclusion, we found that miR-744-5p was negatively related to the progression and metastasis of osteosarcoma via the downregulation of TGFB1 through the p38 MAPK signaling pathway." (PMID 35593122, 2022). "We next investigated TGFβ1 levels in EVs derived from human osteosarcoma cell lines with different metastatic potential by ELISA." (PMID 32751693, 2020). "On the other hand, relative to other pediatric solid tumor types, we observed osteosarcoma to exhibit pronounced expression of additional immunosuppressive molecules particularly TGFB1 and CSF1R, where median expression was the highest among all tumor types in the study cohort." (PMID 34818552, 2021). "Another research demonstrated that SWCNTs could specifically inhibit the process of TGFβ1-induced osteosarcoma cells dedifferentiation, prevent the stem cell phenotypes acquisition and reduce the osteosarcoma stem cells viability." (PMID 31892974, 2020). "Furthermore, we demonstrate, through the use of transforming growth factor beta receptor 1 (TGFBR1) inhibitors and CRISPR-Cas9-mediated knockouts, that TGFβ1 present in osteosarcoma cell-derived EVs is responsible for lung fibroblast differentiation." (PMID 32751693, 2020). "We deliver strong evidence that osteosarcoma cell-derived EVs can induce lung fibroblast reprogramming and thereby direct fibroblast activation and differentiation towards a myofibroblast/CAF phenotype through EV-associated TGFβ1 and SMAD2 pathway activation." (PMID 32751693, 2020). "Similar to that observed in H2O2-treated U2OS osteosarcoma cells, co-immunoprecipitation assays revealed modest TGFβ1 or Dex-regulated interaction between GR and 14-3-3ζ that was further enhanced following combinatorial treatment of cells with both TGFβ1 and Dex." (PMID 32357907, 2020). "Transforming growth factor beta 1 (TGFβ1), a well-known ECM formation activator, induces ADAMTS2 mRNA and protein levels in MG-63 cells (i.e., human osteosarcoma cells of fibroblastic origin)." (PMID 40837410, 2025). "Both the pharmacological inhibition of TGFβ downstream signaling in fibroblasts and CRISPR-Cas9 mediated gene deletion of TGFβ1 in osteosarcoma cells prevented osteosarcoma-derived EVs from activating lung fibroblasts in vitro." (PMID 32751693, 2020). "Meanwhile, some hub genes have been reported involved in the tumorigenesis and progression of osteosarcoma, such as ITGAV, POSTN, COL1A1, TGFB1, TGFB3, and ITGAV." (PMID 32582282, 2020). "Moreover, MG63 osteosarcoma cell-derived EVs induced M2 macrophage differentiation and also enhanced expression of cytokine transcripts, such as IL10, VEGF and TGFB1 in vivo." (PMID 35493080, 2022).
osteosarcoma (continued). "Nonetheless, although this study claimed that T cell immunoglobulin and mucin domain containing-3 (TIM-3) was the mediator of such effect transferred by osteosarcoma-derived EVs, the mechanisms by which this protein drives immunosuppression and TGFB1 expression were not fully investigated." (PMID 35493080, 2022).
osteoarthritis (222 papers, 2007 to 2026). A noninflammatory degenerative joint disease occurring chiefly in older persons, characterized by degeneration of the articular cartilage, hypertrophy of bone at the margins and changes in the synovial membrane. "Drawing on current research, future studies should explore the precise mechanisms underlying the TGFB1/Nrf2 signaling pathway and the role of neutrophils in osteoarthritis progression." (PMID 39160590, 2024). "This study elucidates how extracellular vesicles derived from mesenchymal stem cells activate the Nrf2 signaling pathway by transporting TGFB1, offering novel insights into the pathophysiological mechanisms underlying osteoarthritis." (PMID 39160590, 2024). "Cai and collaborators have designed and synthesized the biomimetic cupper sulfide@phosphatidylcholine (CuS@PC) NPs loaded with pDNA encoding transforming growth factor-beta 1 (TGF-β1) to operate MSCs for increased osteoarthritis treatment via cartilage regeneration." (PMID 38926780, 2024). "Both of these proteins have recently been proposed to contribute to TGFβ1 signaling in early cartilage development and alterations within TGFβ1 signaling have been linked to osteoarthritis, whilst COMP itself has recently been identified as a TGFβ-responsive gene." (PMID 23951406, 2013). "To further study the involvement of TGFB1 in the protection of intra-articular cartilage by GMOCS-exos in a rat model of osteoarthritis, we suppressed TGFB1 expression using sh-TGFB1 in rats." (PMID 39160590, 2024). "Our research has discovered that extracellular vesicles derived from mesenchymal stem cells found in bone marrow, which contain TGFB1, possess the potential to regulate the progression of osteoarthritis." (PMID 39160590, 2024). "This study aims to investigate the impact of TGFB1, carried by MSCs exosomes, on neutrophil function in osteoarthritis (OA) via the Nrf2 signaling pathway." (PMID 39160590, 2024). "This study sheds light on a promising therapeutic strategy for osteoarthritis through GMOCS-Exos-mediated TGFB1/Nrf2 pathway modulation." (PMID 39160590, 2024). "This study investigated the mechanism of the extracellular matrix-mimicking hydrogel-mediated TGFB1/Nrf2 signaling pathway in osteoarthritis using bone marrow mesenchymal stem cell-derived exosomes (BMSCs-Exos)." (PMID 39160590, 2024). "A significant enhancement of the propulsion times of affected legs was detected in a murine model of transforming growth factor β1 (TGFβ1)-induced osteoarthritis." (PMID 34585962, 2021). "Asporin, a class I small leucine-rich proteoglycan, regulates chondrogenesis, and inhibits TGFβ1-induced expression of matrix genes, acting as a critical regulator of joint diseases, including osteoarthritis." (PMID 32656202, 2020). "Some of the cytokines shown to increase in osteoarthritis are IL-18, TGFβ1, IL-1 receptor (IL-1R), and IL-1 alpha (IL-1α)." (PMID 32189997, 2020). "A study conducted among patients with osteoarthritis showed that IL-1β, IL-6, IL-8, IL-18, IL-17, IL-22, and transforming growth factor-beta 1 (TGFβ1) were increased in the inflamed synovium tissues compared to the noninflamed tissues." (PMID 32189997, 2020). "The mean synovial platelet-derived growth factor-BB and transforming growth factor-beta 1 concentrations were increased for both groups but significantly lowered in the group with osteoarthritis on Day 1 compared to normal joints." (PMID 31170778, 2019). "Transforming growth factor β1 (TGFβ1) has been investigated in osteoarthritis and chondrocytes for years." (PMID 29207646, 2017). "Blockage of TGFβ1 signaling resulted in cartilage degeneration and osteoarthritis-like tissue formation." (PMID 29207646, 2017). "However, TGFB1 signaling is deregulated in osteoarthritis and high concentrations of TGFB1 can be found in the synovial fluids of patients with this disease." (PMID 30717351, 2019).
osteoarthritis (continued). "Instead, targeting TGFβ1 or relevant receptors might be a strategy to prevent or alleviate progression of osteoarthritis." (PMID 29207646, 2017). "Therefore, chondrocytes with TGFβ1 stimulation might also play a role in angiogenesis in osteoarthritis." (PMID 29207646, 2017). "However, whether TGFβ1 stimulates chondrocyte proliferation and cartilage regeneration in osteoarthritis (OA) remains elusive, especially in the context of different treatment and tissue environments." (PMID 29207646, 2017). "Overexpression of transforming growth factor-beta 1 (TGF-β1) and subchondral bone remodeling play key roles in osteoarthritis (OA)." (PMID 33259777, 2021). "Therefore, application of TGFβ1 for chondrocyte culture in practice should be considered prudentially and targeting TGFβ1 or relevant receptors to block the signaling pathway might be a strategy to prevent or alleviate progression of osteoarthritis." (PMID 29207646, 2017). "In fact, by using primary osteoblast cultures from bone samples of osteoarthritis patients, dysregulated expression of TWIST1, TGFβ1, and SMAD3 mRNA has been observed (Kumarasinghe, Sullivan, Kuliwaba, Fazzalari, & Atkins, 2012)." (PMID 28425564, 2017). "Furthermore, mouse tissues afflicted with late-stage osteoarthritis after destabilization surgery expressed HTRA1, which diminished the expression of transforming growth factor beta 1 (TGF-β1)." (PMID 38927030, 2024). "Further studies revealed that TGFβ1 could induce the aggregation of mesenchymal stem cells (MSC) and induce the blood vessel formation in osteoarthritis cartilage." (PMID 29207646, 2017). "In patients with osteoarthritis, there was high level of TGFβ1 in subchondral bone and inhibition of the activity of TGFβ1 effectively attenuated the degradation of cartilage ECM, suggesting that high level of TGFβ1 in subchondral bone be a trigger of osteoarthritis." (PMID 29207646, 2017).
bladder cancer (218 papers, 2002 to 2025). "It was found that TGFβ1 from the cancer associated fibroblasts can induce EMT in the urinary bladder cancer cells by up-regulating ZEB2-AS1 and ZEB2 protein level." (PMID 29258558, 2017). "TGFB1 c.29C > T substitution (rs1800470) correlates with an increased risk of bladder cancer." (PMID 31842336, 2019). "In addition, TGFβ1 secreted by cancer-associated fibroblasts induces EMT of bladder cancer cells through lncRNA-ZEB2NAT." (PMID 30250403, 2018). "However, to the best of our knowledge, the specific role of miR-221 in the TGFβ1-induced EMT in bladder cancer and the mechanisms underlying its effects remain unknown." (PMID 25928257, 2015). "Selective inhibition of latent TGFβ1, the predominantly expressed TGFβ isoform in cancers, is efficient in potentiating the anti-cancer immune response in a murine model of refractory bladder cancer but yet to be evaluated clinically." (PMID 36568151, 2022). "In bladder cancer cell lines, TGFβ1 treatment significantly elevated NRP2 mRNA by five-fold while only a minor increase of the NRP2 protein level was observed in our hands." (PMID 33918816, 2021). "TGFβ1 secreted by CAFs induces epithelial-mesenchymal transition and invasion of bladder cancer cells via lncRNA-ZEB2NAT." (PMID 31448238, 2019). "Our study demonstrated that miR-221 facilitated TGFβ1-induced EMT in human bladder cancer cells by targeting STMN1 and represented a promising therapeutic target in the process of metastasis." (PMID 25928257, 2015). "The clinical association of TGFβ1, ZEB2NAT transcripts and ZEB2 protein were further confirmed in 17 human bladder cancer samples." (PMID 26152796, 2015). "Downstream targets of TGFβ1 signaling in three bladder cancer cell lines under CAF-CM stimulation were further tested." (PMID 26152796, 2015). "We also reported that lncRNA-ZEB2NAT mediates bladder cancer cell invasion, which is induced by TGFβ1." (PMID 26152796, 2015). "Taken together, our findings demonstrate for the first time that miR-221 can facilitate the TGFβ1-induced EMT process in human bladder cancer cells by suppressing STMN1." (PMID 25928257, 2015). "Further studies targeting STMN1 and the mechanism of miR-221 regulation by TGFβ1 induction will provide promising and feasible options for the treatment and prevention of human bladder cancer." (PMID 25928257, 2015). "In the present study, we found that miR-221 expression is specifically upregulated in TGFβ1-responsive bladder cancer cells and contributes significantly to the development of the EMT phenotype." (PMID 25928257, 2015). "We used qRT-PCR and western blot to accurately measure the levels of miR-221, STMN1 and EMT markers in TGFβ1 induced EMT of bladder cancer cells." (PMID 25928257, 2015). "In this sense, it has been revealed that PRELP interacts with TGFβ1, leading to the suppression of canonical SMAD signal transduction and suggested that PRELP suppresses bladder cancer progression by reversing the epithelial-mesenchymal transition through inhibition of TGFβ1 signaling pathway." (PMID 40634432, 2025). "miR-221 expression was greatly increased by TGFβ1 in bladder cancer cell." (PMID 25928257, 2015). "In this study, STMN1 was downregulated by TGFβ1 in bladder cancer." (PMID 25928257, 2015). "To explore whether miR-221 is involved in TGFβ1-induced EMT in human bladder cancer cells, we first attempted to determine the expression level of miR-221 before/after TGFβ1 treatment." (PMID 25928257, 2015). "In conclusion, miR-221 inhibition attenuated TGFβ1-induced EMT in bladder cancer cells." (PMID 25928257, 2015). "In the tumorigenesis of urinary bladder carcinoma, TGFβ1 is also considered a crucial molecule." (PMID 21483670, 2011). "TGFβ1 signaling played a major role in the response of bladder cancer cells to ECM." (PMID 16412233, 2006). "An important role for TGFβ1 in bladder cancer has been proposed." (PMID 16412233, 2006).
bladder cancer (continued). "Because incubation with TGFβ1 resulted in increasing miR-221 levels in both RT4 and T24 cells, we silenced miR-221 to test whether miR-221 is involved in motility changes in bladder cancer cells, aiming to examine the specific role of miR-221 in TGFβ1-induced EMT." (PMID 25928257, 2015). "In both cell lines, VIM-AS1 and Vimentin expression levels were prominently occasioned by TGFβ1 incentive in a concentration-dependent manner, indicating that VIM-AS1 is related to EMT in bladder cancer and cancer metastasis." (PMID 33902589, 2021). "The knockdown of EIF5A2 in bladder cancer suggests that by increasing the enrichment of STAT3, EIF5A2 elevated TGF TGFβ1 expression by inducing EMT." (PMID 32605067, 2020). "Consistently, TGFβ1 mRNA expression is positively correlated with ZEB2NAT transcript and ZEB2 protein levels in human bladder cancer specimens." (PMID 26152796, 2015). "To further assess the effects of miR-221 on TGFβ1-induced EMT, we transfected control and miR-221 inhibitor into T24 and RT4 cells, and then cells were treated with TGFβ1, and detected the effects of miR-221 on TGFβ1-induced EMT in bladder cancer cells." (PMID 25928257, 2015). "Secreted TGFβ1 induces EMT and cancer cell invasion in all of three bladder cancer cell lines." (PMID 26152796, 2015). "Based on current data on BGN-mediated modulation of the TGFβ pathway and the stimulatory role of TGFβ1 on bladder cancer cells, it can be assumed that effects of BGN on the availability of TGFβ1 may be involved in the anti-proliferative effect of BGN in bladder cancer." (PMID 24223213, 2013).